PICSAR (P38 inhibited cutaneous squamous cell carcinoma associated lincRNA)
Synonyms: NLC1-C; PRED74; lnc-NLC1-C; C21orf113; LINC00162; NCRNA00162; NLC1C
Gene: Long non-coding RNA gene on chromosome 21 (44,999,140 to 45,004,753, reverse strand). Ensembl gene ENSG00000275874.
Diseases named in the same sentence as PICSAR in open-access papers:
PICSAR is named in the same sentence as 16 diseases in open-access papers, as found by Europe PMC text mining. Sharing a sentence is not in itself a finding about the gene and the disease. The quoted sentences say what the papers report.
cutaneous squamous cell carcinoma (2 papers, 2017 to 2020). "LINC00162 is P38 inhibited cutaneous squamous cell carcinoma associated lincRNA, also named as PICSAR and NLC1-C." (PMID 28881680, 2017).
actinic keratosis (1 paper, 2020). A precancerous lesion of the skin composed of atypical keratinocytes. "Elevated expression of PICSAR was also noted in vivo in actinic keratosis and cSCC in situ, suggesting a role for PICSAR at the early stage of epidermal carcinogenesis." (PMID 32462404, 2020).
tumour (1 paper, 2021). "Among them, the oncogenic LINC00162 (also named PICSAR) and HOTAIR and the tumour suppressor LINC00520." (PMID 35201472, 2021).
PICSAR also shares sentences with these, for which no sentence is quoted: cancer (4 papers); male infertility (2); testicular embryonal carcinoma (2); bladder cancer (1); breast carcinoma (1); embryonal carcinoma (1); glioma (1); infertile (1); narcolepsy (1); pancreatic cancer (1); testicular cancer (1); testicular tumors (1); thyroid cancer (1).